SLC7A11 (solute carrier family 7 member 11)
Diseases named in the same sentence as SLC7A11 in open-access papers (continued):
Sharing a sentence is not in itself a finding about the gene and the disease.
tumor (continued). "Furthermore, the results of immunohistochemistry suggested that eIF5A was significantly reduced (g), and the ferroptosis marker proteins (FANCD2, SLC7A11, and HSPb1) were significantly downregulated in the tumor tissues of sh-eIF5A group mice (h)." (PMID 35874632, 2022). "However, the role of polycomb repressive complex 1-mediated transcriptional repression of SLC7A11 in ferroptosis and tumor development awaits further investigation." (PMID 36147464, 2022). "Indeed, in culture, T-cell proliferation is strongly dependent on SLC7A11 expression, but SLC7A11 is dispensable for T-cell proliferation and memory immune responses to the tumor in vivo." (PMID 35011702, 2022). "On the one hand, cytokines secreted by immune cells could affect the expression of SLC7A11 in tumours." (PMID 35804831, 2022). "Not only SLC7A11 expression, but also the stabilisation of the SLC7A11 protein could promote tumour growth by inhibiting ferroptosis." (PMID 35804831, 2022). "Ultimately, increased SLC7A11 inhibits ferroptosis and promotes tumor progression." (PMID 36147463, 2022). "CD8+ T cells secreted IFN-γ, which could downregulate SLC7A11 expression and affect tumour cell growth." (PMID 35804831, 2022). "IFNγ-mediated suppression of SLC7A11 results in enhanced tumor lipid oxidation and ferroptosis." (PMID 36003368, 2022). "Tumor cells acquire Cys indirectly via peripheral glutamine using System Xc− as a carrier, SLC7A11 is upregulated in one-third of TNBC cells in vivo, and limiting glutamine uptake or inhibiting System Xc− activity increases intracellular ROS levels and slows TNBC metabolism." (PMID 36105219, 2022). "Furthermore, we revealed the competitive regulation of YY family members on tumor cell redox homeostasis via competitive transcriptional regulation of SLC7A11." (PMID 35246964, 2022). "In vivo, BAP1 inhibited tumor growth partly by repressing SLC7A11 and inducing ferroptosis." (PMID 35399527, 2022). "SLC7A11-mediated ferroptosis resistance may contribute to proto-oncogene KRAS-driven tumour growth and development." (PMID 35804831, 2022). "In addition, SLC7A11-related interactions between immune cells and tumour cells affect tumour survival and proliferation." (PMID 35804831, 2022). "Meanwhile, the overexpression of SLC7A11 can affect the expression of chemokines, leading to the infiltration of immune cells such as CD8+ T cells/neutrophils, and deficiency of other immune cells, and causes immunosuppression of tumor cells." (PMID 35517862, 2022). "It appears that DUBs could modulate SLC7A11 expression in line with E3s and further influence tumor progression by inducing ferroptosis." (PMID 36147464, 2022). "Subsequently, western blot showed that the expression levels of E-cadherin and HO-1 were notably enhanced by Lut or erastin, whereas MMP2, vimentin, GPX4, and SLC7A11 expression levels in tumor tissues treated with Lut or erastin were remarkably inhibited compared with those in the controls." (PMID 35656025, 2022). "SLC7A11 overexpression abrogated the tumor‐suppressive effect of YY2 overexpression." (PMID 35246964, 2022). "Moreover, the tumor suppressor gene, BRCA1-associated protein 1 (BAP1), was found to reduce SLC7A11 expression by decreasing histone 2A ubiquitination occupancy on its promoter in human cancer, which consequently resulted in increased ferroptosis." (PMID 35531466, 2022). "Furthermore, YY2 and YY1 bind competitively to the same DNA binding site in the SLC7A11 promoter and antagonistically regulate tumor cell ferroptosis, thus suggesting the molecular mechanism underlying their opposite regulation on tumorigenesis." (PMID 35246964, 2022). "Overall, DUBs that regulate SLC7A11 are complicated in tumor cells." (PMID 36147464, 2022).
tumor (continued). "SLC7A11 has become a central hub linking ferroptosis to its suppressive function on tumor." (PMID 35517862, 2022). "Furthermore, IFNγ downregulates the expression of SLC3A2 and SLC7A11, two subunits of the glutamate–cystine antiporter system xc−, impairs the uptake of cystine by tumor cells, and subsequently promotes tumor cell lipid peroxidation and ferroptosis." (PMID 34385592, 2022). "Furthermore, IFNγ and radiotherapy synergistically repress SLC7A11 expression, further enhancing lipid oxidation and ferroptosis in tumor cells." (PMID 34826064, 2022). "To determine whether SLC7A11-positive macrophages exist in human cancers, we evaluated SLC7A11-expressing macrophages using a publicly available single-cell RNA-seq dataset consisting of tumor-infiltrating myeloid cells in pan-cancer." (PMID 36470862, 2022). "Interestingly, dysregulated cholesterol homeostasis resulting from 27 H C increases breast cancer growth by ferroptosis evasion, which shows that targeting the tumor microenvironment is promising in lipid metabolism because IFNγ downregulates SLC7A11." (PMID 36339539, 2022). "Therefore, SLC7A11 is upregulated in many tumour cells compared with paired cells from normal tissue, as evidenced by bioinformatic analysis from The TCGA database." (PMID 35804831, 2022). "YY2 competes with YY1 to bind to SLC7A11 promoter and regulates it antagonistically, resulting in the opposite regulation on glutathione synthesis, ferroptosis, and tumor progression, indicating that YY2/YY1 homeostasis is crucial for maintaining redox homeostasis in tumors." (PMID 35246964, 2022). "Therefore, inhibition of the GSH/GPX4 pathway by SLC7A11 in combination with radiotherapy induces ferroptosis in tumor cells has strong application." (PMID 36589232, 2022). "This indicated that sulfasalazine could increase the methionine dependence of tumor cells by repressing SLC7A11." (PMID 35123415, 2022). "Univariate Cox proportional hazard model revealed that SLC7A11 (HR = 1.30257, p = 0.00001), race (HR = 1.141,229, p = 0.16372), age (HR = 0.07752, p = 0.07752), tumor stage (HR = 1.37612, p = 0.00066) and grade (HR = 1.12104, p = 0.33867) were all shown to be risk factors for LIHC." (PMID 36267158, 2022). "In addition, ARF can activate the expression of SLC7A11 by inhibiting the transcription of Nrf2, promote ferroptosis by regulating the sensitivity of tumor cells to oxidative stress, and suppress the resistance to drugs." (PMID 35668934, 2022). "For example, SLC7A11 plays a crucial pharmacological role in tumours—especially in CNS tumours." (PMID 35804831, 2022). "Moreover, mutations of YY2 zinc‐finger domains in clinical cancer patients abrogate YY2/SLC7A11 axis and tumor cell ferroptosis." (PMID 35246964, 2022). "In addition, interferon gamma released by CD8+ T cells downregulates the expression of SLC3A2 and SLC7A11, impairing the uptake of cystine by tumor cells and thus promoting lipid peroxidation and iron weakness in tumor cells." (PMID 36012134, 2022). "Of particular relevance to clinical data, the authors found that the expression of SLC7A11 was inversely correlated with the frequency of tumor infiltrating CD8 T cells in human melanoma tumor tissues and that the ferroptosis signature was positively correlated with CD8 T cell effector capacity." (PMID 35065965, 2022). "Increased SLC7A11 expression correlates with tumor invasion and prognosis in patients with GBM." (PMID 36072803, 2022). "Spearman correlation analysis exhibited a significant positive correlation between SLC7A11 and PD-L1 expression (p = 0.001, Spearman = 0.18), indicating that SLC7A11 may be a predictive biomarker for tumor immune checkpoint inhibitors (ICIs) therapy." (PMID 36267158, 2022). "In tumor cells, inhibition of the expression and transport activity of SLC7A11 results in decreased uptake of cystine by the cell and may trigger ferroptosis of tumor cells." (PMID 36238649, 2022).
tumor (continued). "Recent studies have shown that SLC7A11 could partially promote tumor growth by inhibiting ferroptosis, so inhibition of System Xc- activity to induce ferroptosis in tumor cells has gradually become a feasible strategy." (PMID 36274142, 2022). "Slc7a11 knockout led to inhibition of tumor growth and increased survival in mice." (PMID 35065965, 2022). "Interestingly, it has been reported that variant isoforms of CD44 containing v8-v10 (CD44v8-10) regulate redox status in cancer cells by stabilizing SLC7A11 and promoting tumor growth, metastasis, and cisplatin resistance." (PMID 35011702, 2022). "SLC7A11 is a cystine/glutamate transporter, which promotes tumor growth and development." (PMID 35846148, 2022). "In addition, SLC7A11 was also shown to be strongly expressed in multiple tumor types in pan-cancer analysis, interacting with multiple ICs, including PD-L1." (PMID 36267158, 2022). "IFN-γ derived from immunotherapy-activated CD8+T cells and radiotherapy-activated ataxia telangiectasia mutated (ATM) can independently or synergistically suppress the expression of SLC7A11 to reduce cystine uptake, enhance tumor lipid oxidation and ferroptosis, and improve tumor control." (PMID 36003368, 2022). "To examine whether YY2 regulation of SLC7A11 was crucial for YY2‐induced tumor ferroptosis, we constructed a vector overexpressing SLC7A11 and two shRNA expression vectors targeting different sites on SLC7A11." (PMID 35246964, 2022). "Furthermore, the GSH/GSSG ratio and MDA concentration in xenograft tumours confirmed the inhibitory effect of SLC7A11 on HB ferroptosis." (PMID 35522946, 2022). "SLC7A11, as the catalytic subunit of the Xc− system, is overexpressed in multiple human tumours." (PMID 35522946, 2022). "Thus, the cancer cells would be able to survive in the harsh tumour microenvironment because GSH generated from the imported cysteine through SLC7A11 can neutralize excessive free radicals." (PMID 35415880, 2022). "Inhibition of SLC7A11 expression facilitates tumour adaptation to a hypoxic microenvironment." (PMID 35804831, 2022). "SLC7A11 is an important oncoprotein, which not only plays a role in defending against oxidative stress and ferroptosis, but also plays a role in influencing malignant tumor behavior and tumor microenvironment." (PMID 35311457, 2022). "IFN-γ released by CD8+T cells may activate the JAK1-STAT1 pathway to inhibit SLC7A11 expression, reducing cystine uptake by tumor cells and leading to iron death." (PMID 36466094, 2022). "The xenograft tumour model demonstrated that deletion of SLC7A11 dramatically suppressed tumour volume and weight, suggesting that SLC7A11 could promote HB tumour growth in vivo." (PMID 35522946, 2022). "In addition, after knockdown of BRD4 or under (+)-JQ1 (an inhibitor of the tumor-driver bromodomain protein BRD4), the expressions of ferroptosis-associated genes GPX4, SLC7A11, and SLC3A2 are downregulated." (PMID 34222241, 2021). "Consequently, OTUB1 promotes tumor development partly via stabilizing SLC7A11 and inhibiting ferroptosis." (PMID 33000412, 2021).
tumor (continued). "Recently, a well-conducted study reported that CD8+ T cells could induce ferroptosis in tumor cells via downregulating the SLC7A11 expression." (PMID 34938318, 2021). "In addition, immunotherapy enhanced tumor lipid oxidation and ferroptosis by repressing SLC7A11 to improve tumor control." (PMID 33954048, 2021). "We additionally investigated whether the inhibition of SLC7A11 expression sensitizes NRF2-overexpressing ESCC tumor cells to RT by inducing ferroptosis." (PMID 34446045, 2021). "NRF2/SLC7A11/ferroptosis-specific therapeutics may provide tumor-specific sensitization to RT in patients with ESCC who develop de novo radioresistance." (PMID 34446045, 2021). "We further examined whether inhibition of SLC7A11 contributes to the anti‐tumour effects of METTL14." (PMID 34609072, 2021). "Similarly, SLC7A11 expression was higher in tumor tissues than in matched adjacent normal tissues (56.5 versus 14.5%, p < 0.001)." (PMID 34446045, 2021). "Importantly, SLC7A11 has emerged as a central hub linking ferroptosis to its proposed tumor suppression function." (PMID 33000412, 2021). "Additionally, interferon-γ from CD8+ T cells can promote tumor cell ferroptosis by downregulating SLC3A2 and SLC7A11, impairing tumor cystine uptake and disrupting tumor cell redox homeostasis." (PMID 34830482, 2021). "A pan-cancer analysis of 32 cancer types revealed that SLC7A11 could potentially regulate 4595 genes as a ceRNA, providing strong support for SLC7A11 activity as a ceRNA in tumor regulation." (PMID 34790572, 2021). "Importantly, ectopic expression of SLC7A11 strongly blocked METTL14‐induced tumour‐suppressive effect in hypoxic HCC." (PMID 34609072, 2021). "As ferroptosis plays crucial roles in both immunity and pulmonary carcinogenesis, the correlation between CISD1, FANCD2, PGD, ASCL3, ATP5MC3, and SLC7A11 expression and tumor immune infiltration in LUAD was evaluated utilizing data obtained from the TIMER database." (PMID 35320929, 2021). "Analysis of gene expression, mutation, DNA methylation, and prognostic value in LUAD revealed CISD1, ATP5MC3, PGD, SLC7A11, ACSL3, and FANCD2 to be significantly upregulated in LUAD and elevated expression of these FRGs to be associated with advanced tumor stage and poor prognosis." (PMID 35320929, 2021). "In these cancers, SLC7A11 is assumed to express majorly in tumor cells and may be regulated by immune cells in stroma like CD8+ T cells." (PMID 34938318, 2021). "Another study revealed that CD8+ T cells released interferon-gamma (IFNγ) promoted ferroptosis-specific lipid peroxidation in tumor cells via downregulating the expression of SLC3A2 and SLC7A11, and in turn, increased ferroptosis contributes to the anti-tumor efficacy of immunotherapy." (PMID 35071242, 2021). "In addition, studies have confirmed that the nuclear transcription factor NRF2 can inhibit the occurrence of ferroptosis in tumor cells by regulating the transcription of SLC7A11, and inhibiting the expression of NRF2 can enhance cell ferroptosis." (PMID 34123855, 2021). "This indicated that SLC7A11 could mobilize the synthesis procedures of nucleotides, FAs, and amino acids to maintain the proliferative consumption of tumor cells." (PMID 34761566, 2021). "Besides, the correlation between SLC7A11 and immune stimulators and inhibitors was complicated and tumor specific." (PMID 34938318, 2021). "In addition, IFN-γ can downregulate the expression of two Glu-cystine antiporter subunits, recombinant solute carrier family 3, member 2 (SLC3A2) and SLC7A11, on the surface of tumor cells." (PMID 34123855, 2021). "It should be noted that not all SLC7A11 expression alterations in cancers can be linked to its presumed function to mitigate ferroptosis and promote tumor development." (PMID 33000412, 2021).
tumor (continued). "Moreover, SLC7A11 is essential for eliciting tumor formation and maintaining tumorigenicity by relieving oxidative stress in some oncogenic KRAS-mutant cancers, such as pancreatic ductal adenocarcinoma, colorectal adenocarcinoma, and lung adenocarcinoma." (PMID 34249928, 2021). "The results showed that the relationship between SLC7A11 and each cell subtype was tumor specific." (PMID 34938318, 2021). "Moreover, the genetic or pharmacological inhibition of xCT/SLC7A11, such as with erastin, hold promise as a therapeutic strategy in several tumours." (PMID 34841108, 2021). "Furthermore, depletion of STAT1 in tumor cells disrupts the IFNγ-mediated SLC7A11 suppression and reverses RSL3-induced ferroptosis." (PMID 34796174, 2021). "Moreover, the decreased tumorigenic ability of SGC-7901 cells led by miR-375 overexpression was rescued by SLC7A11 overexpression, which was evident by the increased tumor formation rate and stem cell frequency." (PMID 34090492, 2021). "Although this review so far has somewhat focused on the anti-ferroptosis function of SLC7A11 in tumor biology (partly because ferroptosis is a relatively recently discovered cell death mechanism), we want to emphasize that SLC7A11’s roles in tumor biology clearly go beyond regulating ferroptosis." (PMID 33000412, 2021). "IFNG (interferon gamma, INFγ)released from CD8+ T cells downregulates the expression of SLC3A2 and SLC7A11, two subunits of the glutamate-cystine antiporter system xc-, inhibits the uptake of cystine by tumor cells, and consequently promotes tumor cell lipid peroxidation and ferroptosis." (PMID 34422642, 2021). "We visualized the top five gene sets enriched in SLC7A11-high or SLC7A11-low tumor samples." (PMID 34938318, 2021). "Meanwhile, overexpression of SLC7A11 could significantly rescue METTL14‐induced tumour‐suppressive effect under hypoxia in HCC." (PMID 34609072, 2021). "To corroborate this hypothesis, we observed a significant correlation between SLC7A11 expression and the amount of iron-loaded Lcn-2 in tumor tissue of ccRCC patients." (PMID 34069743, 2021). "An in vivo study showed that inducing tumor-selective ferroptosis via deletion of a system xC-subunit (SLC7A11) was dramatically contributing to the inhibition of the growth of pancreatic ductal adenocarcinoma, which is one of the most lethal solid organ malignancies." (PMID 34938318, 2021). "Compared to the control group, downregulation of SLC7A11 significantly inhibited tumour growth." (PMID 34609072, 2021). "Moreover, IFNγ released by CD8+ T cells inhibits expression of SLC3A2 and SLC7A11 on tumor cells, leading to tumor ferroptosis." (PMID 33801234, 2021). "Therefore, we knocked down ATF4 (siATF4) in renal CAKI1 tumor cells and compared the expression of SLC7A11, GCLM, and GLS after 1 and 24 h of hLcn-2 stimulation to scRNA-treated cells." (PMID 34069743, 2021). "Given the obviously differential expression of SLC7A11 observed between tumor and normal samples, we further investigate whether SLC7A11 expression influences patients’ prognosis." (PMID 34938318, 2021). "From these findings, we conclude that sorafenib does not qualify as a bona fide ferroptosis inducer and that ferroptosis induced by system xc− inhibitors can only be achieved in a fraction of tumor cell lines despite robust expression of SLC7A11, the substrate-specific subunit of system xc−." (PMID 34257282, 2021).